SENCR (smooth muscle and endothelial cell enriched migration/differentiation-associated lncRNA)
Synonyms: FLI1-AS1; lncRNA9
Gene: Long non-coding RNA gene on chromosome 11 (128,691,664 to 128,696,038, reverse strand). Ensembl gene ENSG00000254703.
Diseases named in the same sentence as SENCR in open-access papers:
SENCR is named in the same sentence as 17 diseases in open-access papers, as found by Europe PMC text mining. Sharing a sentence is not in itself a finding about the gene and the disease. The quoted sentences say what the papers report.
atherosclerosis (6 papers, 2016 to 2025). A disease characterized by the build-up of fatty material and calcium deposition in the arterial wall resulting in partial or complete occlusion of the arterial lumen. "Emerging evidence indicates that smooth muscle and endothelial cell-enriched migration/differentiation-associated lncRNA SENCR is involved in vascular dysfunction and atherosclerosis by modulating vascular smooth muscle cell phenotypes or vascular remodeling." (PMID 40354352, 2025). "Emerging evidence indicates that the functional features of SENCR in atherosclerosis are the basis of VC, demonstrating its potential role in VC." (PMID 40354352, 2025). "It was demonstrated that SENCR regulates the proliferation, migration and phenotype of SMCs, and knockdown of SENCR could effectively promote the proliferation of SMCs and the development of atherosclerosis." (PMID 32903173, 2021).
coronary artery disease (4 papers, 2016 to 2021). "SENCR expression was diminished in vascular ECs derived from superficial forearm veins of patients with critical limb ischemia and pre-mature coronary artery disease." (PMID 32241300, 2020). "SENCR expression was altered in vascular tissue and cells derived from patients with critical limb ischemia and premature coronary artery disease compared to controls." (PMID 26898221, 2016). "However, SENCR was proved to be downregulated in the plasma of patients with coronary heart disease." (PMID 32903173, 2021). "Subsequently, lower levels of SENCR in human critical limb ischemia and in the ECs of patients with premature coronary artery disease were observed, again supporting that hypothesis that SENCR is downregulated in pathology." (PMID 30524312, 2018). "Finally, we revealed an alteration of SENCR in vascular tissue and EC derived from patients with critical limb ischemia and premature coronary artery disease." (PMID 26898221, 2016).
Ewing sarcoma (2 papers, 2022 to 2024). A small round cell tumor that lacks morphologic, immunohistochemical, and electron microscopic evidence of neuroectodermal differentiation. "SENCR is closely associated with the proliferation and migration of vascular smooth muscle cells, and the polymorphic variants of SENCR affect the susceptibility and progression of Ewing sarcoma." (PMID 39723224, 2024).
leukemia (2 papers, 2024 to 2025). A malignant (clonal) hematologic disorder, involving hematopoietic stem cells and characterized by the presence of primitive or atypical myeloid or lymphoid cells in the bone marrow and the blood. "To further substantiate the clinical significance of the m6A-associated lncRNAs in leukemia, we also examined the expression of LN989, PROX1-AS1, SENCR, LN892, and KIF25-AS1 in AML patients, who received nilotinib twice daily after induction and consolidation chemotherapy." (PMID 41203598, 2025). "Consistently, expression of LN892 and SENCR in GEPIA as well as PROX1-AS1 and KIF25-AS1 in Bloodspot (Leukemia MILE Study) is much higher in leukemia patients than those in normal donors with barely or undetectable expression of LN892 in both datasets." (PMID 39764125, 2024). "Consistently, the expressions of LN892 and SENCR in GEPIA, as well as PROX1-AS1 and KIF25-AS1 in Bloodspot (Leukemia MILE Study), are much higher in leukemia patients than those in normal donors, with barely or undetectable expression of LN892 in both datasets." (PMID 41203598, 2025). "Moreover, higher levels of LN989, SENCR, LN892 and KIF25-AS1 tend to predict poorer survival in leukemia patients from the TCGA study using two different comparisons." (PMID 39764125, 2024). "By analyzing a gene expression profile resulting from SENCR knockdown, we identified a downstream mediator, PI3K signaling, which represents a central regulatory node controlling cell proliferation and apoptosis, and plays a critical role in leukemia drug resistance." (PMID 41203598, 2025).
lung cancer (2 papers, 2024 to 2025). A malignant neoplasm involving the lung. "Lastly, SENCR's involvement in vascular development and its newly discovered contribution to cisplatin resistance in non‐small cell lung cancer highlight the expansive impact of lncRNAs on cancer biology and treatment resistance." (PMID 39324703, 2024).
type 2 diabetes (2 papers, 2016 to 2022). "A close correlation between circulating H19, HOTAIR, MIAT and SENCR levels was also observed in the type 2 diabetes group." (PMID 27874027, 2016). "Type 2 diabetes patients in the fourth quartile of circulating MIAT or SENCR levels showed a higher LVMV-ratio than those in lower quartiles (P < 0.050)." (PMID 27874027, 2016). "Our data demonstrate that circulating levels of LIPCAR and MIAT or SENCR may constitute novel biomarkers of LV diastolic function and remodelling, respectively, in patients with well-controlled type 2 diabetes." (PMID 27874027, 2016). "SENCR is an antisense cytoplasmic lncRNA involved in regulating VSMC phenotype and migration ability, as well as proliferation in type II diabetes mice exposed to high glucose levels." (PMID 36671717, 2022). "Circulating levels of LIPCAR, SENCR and MIAT were further evaluated in a validation study of 30 men with well-controlled type 2 diabetes." (PMID 27874027, 2016).
breast carcinoma (1 paper, 2022). "The current study analyzed the possible association of the lncRNA SENCR rs12420823 variant with breast cancer risk and prognosis." (PMID 36360233, 2022). "In the present study, it was shown that SENCR rs12420823 SNP could be associated with breast cancer risk and poor prognosis in terms of a higher risk of recurrence and shorter survival times." (PMID 36360233, 2022).
colon cancer (1 paper, 2020). "Noticeably, lncRNA SENCR could interact with 356 mRNA in colon cancer." (PMID 33329694, 2020).
diabetic cardiomyopathy (1 paper, 2025). Diabetic cardiomyopathy is a disorder of the heart muscle in people with diabetes. "SENCR, which has been shown to significantly influence vascular smooth muscle cell (VSMC) phenotypes and vascular remodelling, is termed “Angio-LncRNA” and plays an important role in vascular diseases, such as diabetic cardiomyopathy, atherosclerotic coronary artery disease and Jacobsen syndrome." (PMID 40668798, 2025).
non-small cell lung carcinoma (1 paper, 2025). A group of at least three distinct histological types of lung cancer, including non-small cell squamous cell carcinoma, adenocarcinoma, and large cell carcinoma. "In the context of cancer, SENCR has been implicated in promoting the proliferation and progression of non-small cell lung cancer (NSCLC) cells through its interaction with miR-1-3p." (PMID 40668798, 2025).
cancer (7 papers, 2020 to 2025). A tumor composed of atypical neoplastic, often pleomorphic cells that invade other tissues. "Because the pathogenic roles of SENCR have been documented in cancer, with limited knowledge available for PROX1-AS1 and LN892, we selected SENCR, but not PROX1-AS1 and LN892, for further mechanistic study." (PMID 41203598, 2025). "However, the role and underlying mechanisms of SENCR in malignant tumors remain largely unexplored." (PMID 39324703, 2024). "To gain further insights into lncRNA-conferred resistant cell growth, we first analyzed a public database (GSE51878) using LncRNA2Target v2.0, in which SENCR was knocked down in cancer cells, to identify lncRNA downstream targets." (PMID 41203598, 2025). "Further, these genes were either downregulated to the highest levels in cells with SENCR knockdown, or well-established resistant genes and/or annotated to have a role in sustaining cancer cell survival and proliferation." (PMID 41203598, 2025). "To gain further insights of lncRNA-conferred resistant cell growth, we first analyzed a public database (GSE51878) using LncRNA2Target v2.0, in which SENCR was knocked down in cancer cells, to identify lncRNA downstream targets." (PMID 39764125, 2024). "SENCR has been extensively studied in the vascular smooth muscle cells and endothelial cells, but recent studies have showed that it also has a role in cancer." (PMID 36244998, 2022). "Studies have found that SENCR is closely related to the progress of several human cancers." (PMID 36160008, 2022). "Previous studies had reported the role of SENCR in multiple human cancers." (PMID 33329694, 2020). "We focused on SENCR, but not PROX1-AS1 and LN892, because the pathogenic roles of SENCR have been documented in cancer, but limited knowledge is available for PROX1-AS1 and LN892." (PMID 39764125, 2024).
SENCR also shares sentences with these, for which no sentence is quoted: cardiovascular diseases (1 paper); hepatocellular carcinoma (1); Jacobsen syndrome (1); limb ischemia (1); lung adenocarcinoma (1); neuroblastoma (1).